TERT (telomerase reverse transcriptase)
Diseases named in the same sentence as TERT in open-access papers (continued):
Sharing a sentence is not in itself a finding about the gene and the disease.
neuroblastoma (continued). "Also, in the case of MYCN amplified tumours, transcriptional up-regulation of TERT is only one of many oncogenic programmes up-regulated in MYCN amplified neuroblastoma cells." (PMID 32375866, 2020). "6-thio-dG has been shown to be effective in-vivo in neuroblastoma models with TERT activation." (PMID 32375866, 2020). "Notably, the analysis of circle integration showed that spcDNA also causes genomic rearrangements by inserting and connecting a region proximal to the TERT gene, finally leading to enhanced TERT expression in neuroblastoma cells." (PMID 32928268, 2020). "Genomic rearrangements involved with upregulation of TERT in particular have furthermore been shown here to involve a wide range of cancer types, expanded from previous observations made in individual cancer types such as kidney chromophobe and neuroblastoma." (PMID 32024823, 2020). "Other potential factors such as TERT rearrangements, ATRX mutations, CCND1 amplification may also perform well in prognosis of neuroblastoma." (PMID 31338261, 2019). "For example, transcription factors of the MYC family (c-MYC and MYCN), which are associated with aggressive pediatric cancers such as medulloblastoma and neuroblastoma, bind to and activate the TERT promoter, resulting in high TERT mRNA levels of MYC- and MYCN-amplified tumors." (PMID 31757062, 2019). "Genomic rearrangements in non-coding regions may lead to massive activation of oncogenes, such as GFI1 (growth factor independent 1 transcriptional factor) in medulloblastoma or TERT (telomerase reverse transcriptase) in neuroblastoma." (PMID 30171420, 2018). "However, in human neuroblastoma TERT rearrangements rarely, if ever, co-occur with MYCN or ATRX alterations." (PMID 29492199, 2018). "They identified TERT alterations, which are associated with aggressive high-risk neuroblastoma, only in tumor-derived cfDNA (not tumor biopsy) from 2 patients." (PMID 29156716, 2017). "The efforts associated with our approach are justified to enable sensitive detection of TERT rearrangements in this molecular high-risk subgroup of neuroblastoma, which does not overlap with cases harboring MYCN amplifications and includes both high-risk and very high–risk disease." (PMID 39760332, 2025). "The poor prognostic risk factors of locoregional neuroblastoma (LR-NB) include age, MYCN or MDM2-CDK4 amplification, 11q, histology, diploidy with ALK or TERT mutations, and ATRX aberrations." (PMID 38730688, 2024). "In addition, the majority of TERT-positive neuroblastoma cells are MYCN-amplified." (PMID 38837897, 2024). "In addition, telomerase-positive neuroblastoma cells have the active chromatin marks H3K9Ac and H3K27Ac in the TERT promoter, while the TERT promoter of neuroblastoma cells with long telomeres are silenced by H3K27me3, suggesting polycomb repression of the TERT locus." (PMID 38837897, 2024). "Furthermore, N-MYC is known to regulate TERT in other cancer types, including neuroblastoma." (PMID 35406427, 2022). "In addition, genomic rearrangements at chromosomal region 5p15.33, located proximal of the telomerase reverse transcriptase gene (TERT) that results in chromosomal changes, DNA methylation and enhanced TERT expression have also been observed in high-risk neuroblastoma samples." (PMID 33585251, 2020). "Several recurrently mutated genes or loci which correlated with high-risk neuroblastoma have been identified, such as ALK mutations or amplifications, PHOX2B mutation, chromosome 1p and 11q deletions, truncating or structural variants of ATRX gene, genomic rearrangements of TERT." (PMID 30405689, 2018). "Longitudinally assessed TERT breakpoint and ALK p.R1275Q copy numbers were highly similar, possibly reflecting their origins in the same neuroblastoma clone." (PMID 39760332, 2025).
neuroblastoma (continued). "In addition, our data demonstrate that TERT promoter DNA methylation is unique in neuroblastoma, with a CpG methylation pattern similar to somatic and stem cells, supporting the hypothesis that neuroblastoma represents an arrested differentiation of sympathetic neuron progenitors." (PMID 38837897, 2024). "To explore the epigenetic control of TERT expression, we leveraged our previously generated WGBS analysis of neuroblastoma." (PMID 38837897, 2024). "On the other hand, neuroblastoma cells with long telomeres, including ALT-positive tumors, show a different epigenetic signature at the TERT promoter." (PMID 38837897, 2024). "This different epigenetic pattern may suggest that neuroblastoma with long telomeres may arise from sympathetic progenitor cells at a developmental stage different from telomerase-dependent neuroblastomas in which the TERT locus is silenced by PRC2 in a DNA methylation valley." (PMID 38837897, 2024). "In this study, we characterized a Swedish neuroblastoma cohort with the focus on telomere maintenance mechanisms (TMMs), i.e., MYCN amplification and the juxtapositioning of TERT and ATRX aberrations." (PMID 38136279, 2023). "In neuroblastoma due to TERT gene rearrangement with super-enhancers, BRD4 is required for TERT gene transcription and neuroblastoma cell proliferation." (PMID 38135679, 2023). "Known neuroblastoma-related genes such as MYCN, TERT, ODC1, CDK4, and MDM2 were recurrently affected by different classes of complex rearrangements including ecDNA, chromothripsis, and CnCs." (PMID 37868040, 2023). "The recent advance of neuroblastoma research with precision medicine approaches demonstrates that tumors in the UH group are also heterogeneous and four distinct subgroups—MYC, TERT, ALT and null—are identified." (PMID 35053227, 2022). "For example, in MYCN-amplified neuroblastoma, MYCN can bind to the promoter of telomerase catalytic subunit TERT, up-regulate and activate the expression of TERT which is a key function of amplified MYCN." (PMID 36187481, 2022). "MYCN is known to activate the TERT gene and the MYCN amplification is the most frequent genomic alteration in neuroblastoma." (PMID 31285550, 2019). "Even when whole-genome sequencing of neuroblastoma was conducted, few recurrent gene alterations (MYCN, ALK, ATRX and TERT) were identified." (PMID 29311760, 2018). "MYCN is a known transcriptional activator of TERT, yet MYCN amplifications were mutually exclusive with TERT rearrangements, as well as ATRX alterations, a gene associated with alternate lengthening of telomeres, suggesting that these alterations may share a similar role in neuroblastoma." (PMID 28587062, 2017). "More recently, genome-wide searches for genetic alterations using whole-exome/genome sequencing have revealed that neuroblastomas, similarly to other pediatric malignancies, have very few additional gene targets, including ATRX, TERT, and RAS pathway genes." (PMID 29296183, 2017). "Down-regulation of MYCN, ID2, TERT and FN1 has been also reported in neuroblastoma cells undergoing differentiation upon exposure to retinoids." (PMID 26893368, 2016). "Unique breakpoint sequences were identified in the TERT locus (chr5:1252600-1345000 encompassing the TERT and CLPTM1L genes; genome assembly GRCh37/hg19), the breakpoint region, according to Peifer and colleagues, in 64 neuroblastomas from 55 patients." (PMID 39760332, 2025). "Here, we show, unlike most cancers, DNA of the TERT promoter is broadly hypomethylated in neuroblastoma." (PMID 38837897, 2024). "In contrast to the MYCN-amplified neuroblastoma cells, the neuroblastoma samples with long telomeres, including cell lines, autopsies and O-PDX tumors, showed repressive chromatin marks, especially H3K27me3 in the same region of the proximal TERT promoter." (PMID 38837897, 2024).
neuroblastoma (continued). "Moreover, treating TERT-negative neuroblastoma cells with two other EZH2 inhibitors (UNC1999 and PF-06821497 acetate) induced the expression of TERT, confirming the role of PCR2 complex in repressing TERT locus in neuroblastoma cells with long telomeres." (PMID 38837897, 2024). "As inhibiting EZH2 led to MYCN-induced TERT expression in neuroblastoma cells with long telomeres, we wondered whether inhibiting EZH2 facilitates MYCN binding to the TERT promoter." (PMID 38837897, 2024). "The TERT locus is repressed by polycomb repressive complex-2 complex in neuroblastoma cells that have long telomeres and do not express TERT." (PMID 38837897, 2024). "Together, these data suggest that TERT is a MYCN target and the TERT promoter hypomethylated region in neuroblastoma may play a role in the regulation of TERT expression." (PMID 38837897, 2024). "However, in neuroblastoma cells with long telomeres, including ALT-positive cells, we observed that the hypomethylation of the TERT promoter extended throughout the TERT promoter CpG island." (PMID 38837897, 2024). "The DNA at the TERT locus, unlike other cancer cells and similar to normal cells, are hypomethylated in telomerase-positive neuroblastoma cells." (PMID 38837897, 2024). "We found that, similar to normal tissues of developing adrenal medulla, the TERT promoter is hypomethylated in all neuroblastoma cells we studied, independent of telomere maintenance status." (PMID 38837897, 2024). "The findings revealed that 12% to 26% of high-risk neuroblastoma tumors, including several MYCN-Amp tumors, had low TERT expression and no ALT activation." (PMID 36860927, 2023). "This drug can target MYC-family-driven, TERT-overexpressing and ALT-phenotype neuroblastomas and it may be considered the core agent in a cocktail of drugs to treat aggressive EUH neuroblastomas." (PMID 35053227, 2022). "Telomerase-mediated TMM in neuroblastoma can be determined by detecting the respective genomic alterations, i.e., amplification of MYCN (MNA) or rearrangements of TERT (TERT RA), or by examining TERT expression levels or telomerase activity." (PMID 36153564, 2022). "There are additional UH neuroblastomas, which do not exhibit MYC-family protein overexpression, TERT overexpression and ATRX (or DAXX) loss." (PMID 35053227, 2022). "cWGTS mapped events in TERT and ATRX in 8 (28%) and 5 (17%) neuroblastoma patients, respectively." (PMID 35585047, 2022). "Minimal to no TERT mRNA expression was observed for ALT-positive neuroblastomas, resulting from epigenetic silencing of the TERT locus by H3K27me3." (PMID 33627664, 2021). "Further studies have shown that although TERT alterations and MYCN amplification do co-exist in a small proportion of cases, there is no overlap between the telomerase expressing and ALT positive neuroblastoma." (PMID 32375866, 2020). "Although the somatic alterations driving TMM’s in the majority of neuroblastoma are well defined, high telomerase expression can occur in the absence of either a TERT translocation or MYCN amplification." (PMID 32375866, 2020). "In neuroblastoma, tumors without detectable TERT mRNA frequently undergo spontaneous regression, whereas TERT expression, and/or its gene amplification or rearrangements are closely associated with a high-risk/aggressive disease and shorter survival." (PMID 31285550, 2019). "Whole-genome sequencing of 108 neuroblastoma cases revealed TERT rearrangements in 23% of stage 3 and 4 cases regardless of MYCN amplification or ATRX mutations and also confirmed this to be an independent prognostic factor." (PMID 30326621, 2018). "Chromosome rearrangements resulting in an increased activation of TERT (telomerase reverse transcriptase) have recently been identified in ~23% of high-stage neuroblastoma with very poor prognosis but no MYCN amplification." (PMID 28035989, 2016).
neuroblastoma (continued). "To develop a ddPCR assay protocol and test its breakpoint detection and sensitivity for breakpoint copy quantification, we turned to the GI-ME-N neuroblastoma cell line, in which a genomic TERT rearrangement was previously reported but not characterized on the level of the DNA sequence." (PMID 39760332, 2025). "We confirmed the telomere maintenance mechanisms in the eight neuroblastoma cell lines by performing telomere-specific FISH, telomere qPCR, and the C-circle assay, and measuring the relative expression of the telomerase catalytic subunit TERT and the RNA template TERC." (PMID 38837897, 2024). "However, additional non-overlapping groups of high-risk neuroblastoma, such as the groups of ‘alternative lengthening of telomeres (ALT)’ and of ‘telomerase gene (TERT) rearrangements’, are associated with a very poor prognosis." (PMID 36980635, 2023). "Moreover, by whole exome sequencing, we demonstrated that NB exo-DNA represents the entire exome and that it carries tumor-specific genetic mutations, including those occurring on known oncogenes and tumor suppressor genes in neuroblastoma (ALK, CHD5, SHANK2, PHOX2B, TERT, FGFR1, and BRAF)." (PMID 33915956, 2021). "These analyses are of utmost relevance in neuroblastomas without MYCN-amplification, TERT rearrangement, and ATRX alterations, as these neuroblastomas are most likely low-risk, but the detection of telomerase overexpression or ALT would still render them high-risk." (PMID 34442335, 2021). "In 2015 it was reported that aggressive neuroblastoma can be divided into 3 almost mutually exclusive subgroups with either MYCN amplification, rearrangements upstream to the telomerase reverse transcriptase (TERT) gene or alternative lengthening of telomeres (ALT)." (PMID 32375866, 2020). "The discovery of rearrangements inducing the overexpression of TERT in the absence of MYCN-amplification or the mechanisms of the alternative lengthening of telomeres (ALT), often due to mutation or deletion of ATRX, identified telomere maintenance as a feature defining high-risk neuroblastomas." (PMID 34442335, 2021). "A neuroblastoma-specific panel using NGS could be developed to identify more comprehensive genomic information to molecularly treat and predict prognosis with sophistication based on genomic characteristics such as MYCN, TERT, ATRX, ALK, ARID1, and telomere length." (PMID 28521285, 2017). "We show that of the total number of cases, an average of 90% of the samples classified as neuroblastoma, while 66% also achieved confident classification into the three NB subclasses: “MYCN-type”, “ALT/TERT TMM positive” and “TMM negative”." (PMID 40713849, 2025). "TERT rearrangements are usually not accompanied by TERT CNVs, in contrast to high-level MYCN amplifications in aggressive neuroblastoma cell clones harboring MYCN breakpoints." (PMID 39760332, 2025). "In the local cohort, 60 samples (60/90; 67%) classified into neuroblastoma subclasses: 27 samples (27/90; 30%) into TMM negative, 26 samples (26/90; 29%) into MYCN type, and seven samples (7/90; 8%) into “ALT/TERT TMM positive” subclass." (PMID 40713849, 2025). "In neuroblastoma cells with long telomeres (SKNMMMYCN SKNJCIMYCN), induction of MYCN resulted in modest or no increase in MYCN enrichment at the TERT promoter." (PMID 38837897, 2024). "Neuroblastomas were previously divided into five groups based on TMMs: TERTp rearrangement, MYCN amplification, TERT expression high, ALT, and no TMM41." (PMID 33420056, 2021).
liver cancer (58 papers, 2015 to 2025). An epithelial or non-epithelial malignant neoplasm that arises from the liver. "Among liver‐associated hotspot mutations, TERT promoter mutations were detected in cfDNA from 10 out of 29 liver cancer patients." (PMID 39748775, 2025). "Data from 117 patients who underwent surgical resection and were confirmed to have a diagnosis of liver cancer with histopathological examination were analyzed to identify histopathological factors associated with TERT C228T-positive liver cancer." (PMID 35306637, 2022). "We investigated the factors associated with TERT C228T and abnormal levels of liver cancer-specific tumor markers (AFP and PIVKAII) in serum samples." (PMID 35306637, 2022). "Data from all 258 patients who were confirmed to have a diagnosis of liver cancer with imaging studies were analyzed to identify clinical factors associated with TERT C228T-positive liver cancer." (PMID 35306637, 2022). "We sequenced the whole exon region of 560 genes in 10 patients with liver cancer and the promoter mutation hotspot of the TERT gene." (PMID 35602894, 2022). "In our study, the mutation rate of TERT was only 11.76%, which is inconsistent with the established high mutation rate in liver cancer." (PMID 33854600, 2021). "In liver cancer, the expression of the TERT gene is activated by different mechanisms including focal amplification, rearrangements, and mutations in the TERT promoter region." (PMID 34359670, 2021). "To treat HCV-associated liver cancer, we proposed a bivalent DNA vaccine against HCV-associated liver cancer based on telomerase reverse transcriptase (TERT) and HCV core, and designed and optimized each of the components." (PMID 34067686, 2021). "Of the 30 patients with liver cancer that had structural variants that affect TERT, we find that 10 of these variants were templated insertion events (mostly cycles)." (PMID 32025012, 2020). "Subsequently, high frequency of TERT promoter mutations has been found in various cancers, including bladder urothelial cancer 11-14, thyroid cancer 15-17, glioma 18-21, liver cancer 22-26, and so on." (PMID 33061812, 2020). "Published data on the analysis of TERT promoter mutations in liver cancer were searched in Medline using the terms (“hepatocellular” OR (“Liver” AND “Cancer”)) AND (“TERT” OR “telomerase”) AND (“Promoter”) AND (“mutation” OR “variation”)." (PMID 28529542, 2017). "Several studies identify recurrent somatic mutations in TERT promoter in various cancers, including liver cancer." (PMID 28460432, 2017). "TERT promoter mutations have been recognized as the earliest and most frequent genetic alterations in liver cancer." (PMID 28529542, 2017). "To determine the combined effect of the rs2853669 (−245T > C) and TERT promoter mutation (−124C > T or −146C > T) on liver cancer survival rates, we first analyzed the overall survival rates of a Korean HCC patient cohort (SMH cohort, n = 93)." (PMID 26575952, 2016). "Our study suggests that the rs2853669 variant combined with the −124C > T mutation in the TERT promoter is a novel risk factor for poor prognosis in liver cancer." (PMID 26575952, 2016). "In conclusion, we demonstrate a substantial role for the rs2853669 in HCC with TERT promoter mutation, which suggests that the combination of the rs2853669 and the mutation indicate poor prognoses in liver cancer." (PMID 26575952, 2016). "Overall 65 (48.5%) liver cancer cases were found positive for TERT promoter mutations comprising 64 out of 127 (50.4%) HCC and 1 out of 4 (25%) CC." (PMID 27276713, 2016). "So far, no studies have considered effect of rs2853669 combined with somatic mutations at the TERT promoter on liver cancer." (PMID 26575952, 2016). "Here, we aim to discover a novel role for the rs2853669 variant and a mechanism for regulating rs2853669 variant-dependent TERT promoter activity in liver cancer." (PMID 26575952, 2016).